RIPK1 (receptor interacting serine/threonine kinase 1)
Diseases named in the same sentence as RIPK1 in open-access papers (continued):
Sharing a sentence is not in itself a finding about the gene and the disease.
tumor (continued). "The four genes have been found to influence tumor progression in HNSCC via necroptosis regulation; Poly (ADP-ribose) polymerase-1 (PARP1), as a chromatin-associated enzyme in DNA repair; and a downstream effector of RIPK1/RIPK3 pathway in necroptosis." (PMID 36349193, 2022). "Although it is generally accepted that necroptotic factors are anti-tumor factors, an astonishing result was discovered recently: that RIPK1, RIPK3, and MLKL may support tumor growth." (PMID 35884370, 2022). "The knockdown of SOX9 by siRNA treatment in a TNBC cell line induced TNBC cell death and reduced invasion by regulating gene expression involved in the cell death pathway including RIPK1 by Chip-seq analysis and reduced tumor growth and lung metastasis by SOX9 knockout in an in vivo animal model." (PMID 35159173, 2022). "While it is conceivable that cell death induction by acidic TME shapes the evolution of tumor cells, it remains unclear what the precise impact of the ASIC1a/RIPK1-dependent cell death pathway would be for a tumor in situ." (PMID 35961983, 2022). "Consequently, ectopic injection of RIPK1-derived necroptotic cells into the tumor microenvironment induces a systemic immune response driven by DCs and CD8+ T cells that promotes antitumor immunity and increased tumor antigen loading." (PMID 36171264, 2022). "Thereby it is reasonable that the combination of AQP1 with RIPK1 at D324 sequence is an obligatory step for TNBC to facilitate the recruitment of caspase-8, aggravate the cleavage of RIPK1, sequester RIPK1 in a quiescent form, and finally unleash tumor progression." (PMID 33980862, 2021). "Our data provide a plausible explanation for why systemic administration of TNF failed as an effective therapy for malignancies: TNF must be delivered by tumor-reactive T cells during cognate interactions with the tumor targets in order to activate RIPK1-dependent cell death and tumor destruction." (PMID 34752416, 2021). "Because AQP1 is expressed in both membrane and cytoplasm of breast cancer cells, but RIPK1 is exclusively localized in the cytoplasm, the localization of AQP1 and RIPK1 in MDA-MB-231, a human TNBC cell line, and 4T1, a mouse TNBC cell line, was assessed respectively by immunofluorescence staining." (PMID 33980862, 2021). "On the other hand, some recent studies suggested that tumor necroptosis may be triggered by death factors and engages RIPK1 and RIPK3 pathway during tumor development." (PMID 33976222, 2021). "RIPK1 expression and NF-κB activation are essential for this tumour suppressive mechanism." (PMID 33602906, 2021). "We found that RIPK1 levels are dramatically decreased in tumor cells." (PMID 33976222, 2021). "The present study revealed both RIPK1/RIPK3/MLKL and RIPK1/caspase-8/caspase-3 pathways were inhibited in TNBC tumor samples and AQP1-expressing cell lines, which is in agreement with our presumption that both RIPK1-dependent necroptosis and apoptosis are attenuated by AQP1." (PMID 33980862, 2021). "Hence, targeting RIPK1 kinase also contributes to the antitumor effect by contrasting the immunosuppressive necroptotic tumor microenvironment." (PMID 33567618, 2021). "The results showed that tumor cells interacting with lymphocytes for 3 h subsequently die by apoptosis, while their interaction with lymphocytes for 24 h leads to the development of RIPK1-dependent necroptosis." (PMID 34206968, 2021). "Additionally, IFN-γ also induces necroptosis in tumor cells through the activity of the serine–threonine kinase RIPK1." (PMID 33807260, 2021). "Furthermore, necroptosis-associated effector proteins RIPK1, RIPK3 and MLKL, identified in the Clinical Proteomic Tumor Analysis Consortium (CPTAC) validation cohort, were all up-regulated in the tumors, in line with our transcriptomic findings." (PMID 33672863, 2021).
tumor (continued). "Mechanistically, this was linked to an increased RIPK1/RIPK3-dependent protein product of PDA cells (SAP130), which promoted cellular immune suppression by tumour infiltrating macrophages expressing the protein receptor (Mincle) that were themselves recruited in a CXCL1-dependent manner." (PMID 31416294, 2019). "In addition, cells engineered to be deficient in RIPK1-mediated mitophagy are better able to form tumors after tail vein injection into immunocompromised mice, suggesting that the capacity of RIPK1-mediated mitophagy to produce ROS may function in a tumor suppressive capacity." (PMID 31434226, 2019). "Because these drugs promote RIPK1 activation, they might promote anti-tumor immunity in part by RIPK1-dependent cytokine production and necroptosis." (PMID 30631429, 2018). "Further investigation of other permeability factors in vivo and whether these ligands can form complexes of RIPK1/RIPK3 will be of interest to determine if these intracellular proteins can be targeted to block several pathways involved in tumor metastasis." (PMID 28151480, 2017). "We therefore next determined the role of RIPK1 in the investigated tumor cell lines." (PMID 24507727, 2014). "Susceptibility/resistance of the investigated tumor cell lines to programmed necrosis seems to primarily depend on expression of the pro-necrotic kinase RIPK3 rather than the related kinase RIPK1 or cell surface expression of TRAIL receptors." (PMID 24507727, 2014). "Our accumulated evidence suggests that the loss of TBK1 and IKKε may sensitize tumor cells to T cell killing and is associated with reduced pro-survival RIPK1 S25 phosphorylation within the TNFR1 complex, thereby promoting RIPK1 activation and subsequent cell death." (PMID 41315176, 2025). "Their direct applicability to the complex tumour microenvironment in humans, and whether RIPK1-driven necroptosis constitutes a widespread and critical cell death pathway in human cancers, remain to be thoroughly validated using more specific tools and clinically relevant models." (PMID 41334873, 2025). "Notably, the complete knockdown of RIPK1 in cancer cells results in profound alterations within the tumour microenvironment, characterised by increased infiltration of effector T cells, reduced presence of immunosuppressive myeloid cells, and augmented secretion of immune-stimulating cytokines." (PMID 41334873, 2025). "When comparing strategies for manipulating RIPK1, direct activation of RIPK1 through the loss of checkpoint kinases such as TBK1/IKKε may exhibit higher efficiency in tumor killing than knockout strategies, such as RIPK1 KO or PROTAC-mediated degradation, which eliminate the protein entirely." (PMID 41315176, 2025). "In constructed mouse models, RIPK1/RIPK3 has the ability to enhance the expression of sin3A‐associated protein 130 (SAP130), CXCL1 and CXCL5, leading to the phenomenon that macrophages polarize towards M2 direction while promoting immunosuppression and tumour metastasis mediated by M2‐type cells." (PMID 38652105, 2024). "Our data suggest that the RIPK1-MLKL associated death/necroptosis pathway may not be involved in the necrosis seen in our treated SKOV3 tumours." (PMID 37503762, 2023). "Intra-tumoral necroptosis not only promoted tumor antigen loading through tumor antigen presenting cells based on RIPK1/ RIPK3 ectopic activation, but also enhanced DC-, and CD8 + T cell-mediated anti-tumor immunity function, which might provide a new idea for current T-cell-based immunotherapy." (PMID 36175606, 2022). "Thus, RIPK1 is a checkpoint kinase governing tumor immunity, targeting RIPK1 maybe a potential therapeutic strategy for cancer treatment." (PMID 39872161, 2022). "Hence, the expression of TNFR1 and of RIPK1/RIPK3/MLKL proteins by tumor cells, in conjunction with the production of TNFα in the tumor microenvironment, could represent novel biomarkers for cisplatin sensitivity in apoptosis-resistant tumors." (PMID 34490126, 2021).
tumor (continued). "Interestingly, RIPK1 protein level is decreased in the isolated tumor cells." (PMID 33976222, 2021). "Together with the observed differential growth in the WT animals, these results showed that an increased susceptibility to RIPK1-dependent cell death (conferred by SHARPIN deficiency) does not result in spontaneous tumor cell death, but rather sensitizes to T cell–mediated tumor destruction." (PMID 34752416, 2021). "The authors suggested that the downregulation of RIPK1 expression promoted by epigenetic changes during tumor progression enables tumor cells to evade anoikis, which may stimulate tumorigenesis by enhancing the metastatic abilities of the tumor cells." (PMID 31122251, 2019). "Importantly, the specific inhibitor of RIPK1, necrostatin-1, could efficiently reduce tumor cell extravasation and metastasis." (PMID 31922095, 2019). "Necroptosis, initiated by Receptor-Interacting Protein Kinase 1 (RIPK1)/RIPK3-MLKL signaling, leads to the release of High Mobility Group Box 1 (HMGB1) and supports cross-presentation of tumor antigens, thus linking cell death to immune surveillance." (PMID 41235238, 2025). "For instance, RIP kinase 3 (RIPK3) and RIPK1 have been demonstrated to have anti-tumorigenic capacity in CRC, although RIPK3-mediated inflammation can induce an immune-suppressive tumor microenvironment (TME), thereby facilitating intestinal tumor progression." (PMID 40959081, 2025). "In terms of clinical strategies, combining RIPK1 degraders with ICB takes advantage of a potent synergy between immune suppression reversal and anti-tumour immune activation." (PMID 41334873, 2025). "TNF recognizes and binds to TNFR2 on the surface of tumor cells, and activated TNFR2 acts on and activates downstream receptor-interacting protein kinase 1 (RIPK1)." (PMID 40013141, 2025). "Treatment of mice with a RIPK1 inhibitor or endothelial cell-specific deletion of RIPK3 significantly reduced tumour cell-induced endothelial necroptosis, tumour cell extravasation, and metastasis." (PMID 41334873, 2025). "By enabling controlled activation of Gasdermin or RIPK1/3–MLKL pathways, such platforms can enhance tumor-specific immune activation while limiting systemic diffusion of DAMPs and minimizing collateral damage to normal tissues." (PMID 41267084, 2025). "Research has shown that regulators of necroptosis, such as RIPK3, RIPK1 (Receptor Interacting Serine/Threonine Kinase 1), and MLKL, play an essential role in modulating immune tumor response." (PMID 40149492, 2025). "The expression and functional status of critical molecules comprising the PANoptosome, including ZBP1, RIPK1, RIPK3, CASP8, and ASC, can have a bidirectional impact on tumor survival, immune recognition, or tumor cell death." (PMID 40422233, 2025). "Inhibiting TBK1/IKKε correlated with reduced RIPK1 S25 phosphorylation, shifted TNF signaling toward cell death, and sensitized tumor cells to CD8+ T cell attacks." (PMID 41315176, 2025). "In pancreatic cancer, elevated RIPK1 and RIPK3 levels enhance tumor migration and invasion, while low MLKL expression is associated with worse outcomes." (PMID 40969770, 2025). "RIPK1, a key regulator of downstream TNF signaling, has been shown to be essential for CD8 T cell-mediated cytotoxicity, as tumor cells can be driven into RIPK1-dependent apoptosis (RDA) under these conditions." (PMID 41315176, 2025). "Pharmacological degradation of RIPK1 remodels the TME and simultaneously induces ICD, thereby effectively reversing the cold tumour phenotype and sensitising tumours to anti-PD-1 therapy." (PMID 41334873, 2025). "An important example is the finding that glucose deprivation instead of RIPK1 led to activation of MLKL and necroptosis by the release of mitochondrial DNA into the cytoplasm of tumor cells in an experimental model of breast cancer." (PMID 39062119, 2024).
tumor (continued). "It was further noted that genes including capase-8, MLKL, FADD, and TRADD were upregulated in the tumor samples, while caspase-7, NLRP3, RIPK1, and RIRP3 were downregulated in expression." (PMID 38553639, 2024). "It has also been shown that treatment of mice with the RIPK1-inhibitor necrostatin-1 (Nec-1s) or endothelial-cell-specific deletion of RIPK3 reduced tumor cell-induced endothelial necroptosis and tumor metastasis in mouse models." (PMID 38553639, 2024). "Subsequently, it was elucidated that the selective inhibition of RIPK1 using GSK’547 induced a repolarization of TAMs toward an immunogenic phenotype, that led to the activation of adaptive immune responses and tumor suppression." (PMID 38576612, 2024). "Activation of receptor-interacting protein kinases (RIPK1, RIPK3) promotes upregulation of chemokines, facilitating the infiltration of CD8 T cells and thereby enhancing anti-tumor immunity." (PMID 38983866, 2024). "Previous mouse models have shown that activation of TRAIL can lead to the activation of RIPK1, thereby inducing inflammatory responses and driving cell death, explaining the anti-tumor role of CXCL11+ TAMs by eliminating tumor cells through TNFSF10-RIPK1." (PMID 39232806, 2024). "Shikonin is the first drug found to act in the RIPK1/RIPK3‐dependent necroptosis pathway and promotes tumour necroptosis." (PMID 38652105, 2024). "Degradation of RIPK1 by LD4172 triggers immunogenic cell death, enhances tumor-infiltrating lymphocyte responses, and sensitizes tumors to anti-PD1 therapy in female C57BL/6J mice." (PMID 39681571, 2024). "A comprehensive search on PubMed revealed a growing number of articles investigating RIPK family genes, particularly RIPK1, RIPK2, RIPK3 and RIPK4, in the context of tumor research." (PMID 38164277, 2024). "Studies indicate that directing interventions towards ZBP1, caspases, NLRP3, RIPK1, and RIPK3 can trigger a robust anti-tumor immune response, facilitating the efficient eradication of cancer cells." (PMID 38553639, 2024). "Degradation of RIPK1 by LD4172 triggered immunogenic cell death (ICD) and enriched tumor-infiltrating lymphocytes and substantially sensitized the tumors to anti-PD1 therapy." (PMID 38659866, 2024). "In mouse models, treatment with the RIPK1 inhibitor necrostatin-1 or the endothelial cell-specific deletion of RIPK3 reduced tumor cell-induced endothelial necroptosis, tumor cell extravasation, and metastasis." (PMID 38994937, 2024). "Another aspect of PANoptosis that can exert anti-tumor immunity is embodied in RIPK3 and RIPK1, which are both essential components for the activation of necroptosis, and a core part of the interactions between the various PANoptosis signaling pathways." (PMID 38553639, 2024). "We analyzed the influence of RIPK1 tag SNPs on the overall survival of different EOC patients stratified by age, FIGO stage, histological type, and tumor stage." (PMID 37996860, 2023). "In conclusion, we demonstrate for the first time that TRAF6 reduces necroptosis in colorectal cancer cells by directly degrading RIPK1 protein levels and inhibiting the RIPK1-RIPK3-MLKL signaling axis, resulting in the promotion of tumor progression." (PMID 36604411, 2023). "While the RIPK1 inhibitor PK68 exhibited a modest reduction in tumor growth when administered as a monotherapy, a significant reduction in tumor growth was observed only when PK68 was combined with anti-PD-1 treatment." (PMID 37865804, 2023). "MLKL, along with RIPK1 and RIPK3, induce neutrophil extracellular traps, allowing them to act as a physical barrier to protect tumor cells from T or NK cell-mediated cytotoxicity." (PMID 37864090, 2023). "Genotype distributions of RIPK1 tag SNPs were analyzed in different groups stratified by EOC patients’ characteristics including age, FIGO stage, histological type and tumor grade." (PMID 37996860, 2023).
tumor (continued). "Top gene hits identified through both screens involved in for example TNFα signaling were CFLAR, MAPK1, RIPK1, TNFRSF1A, and ICAM1, highlighting their role in regulating tumor sensitivity to TNF-α-induced cell death." (PMID 37732732, 2023). "Necroptosis can activate RIPK1 and RIPK3 in the tumor microenvironment (TME) to promote antitumor immunity." (PMID 35756487, 2022). "Necroptosis is a form of programmed cell death regulated by three major mediators, RIPK1, RIPK3, and MLKL, is a key process in cancer biology, including tumor initiation and progression, invasion and migration, and tumor immunosuppression." (PMID 35965497, 2022). "In previous studies about COAD and necroptosis, the tumor-suppressing effects of RIPK3 and RIPK1 have been studied in COAD." (PMID 36505813, 2022). "RIPK1 inhibitor necrostatin-1 or endothelial-cell-specific RIPK3 deletion inhibited tumor cell-induced endothelial necroptosis, tumor cell extravasation, and metastasis in mice." (PMID 36186479, 2022). "For example, knocking down RIPK1, RIPK3, and MLKL in colorectal and esophageal cancer cells inhibits tumor growth by reducing NF-κB activity." (PMID 36291937, 2022). "Necroptosis is a novel form of programmed cell death distinct from apoptosis that enhances CD8+ T cell-mediated anti-tumor immunity via a mechanism involving RIPK3 and RIPK1 activation in the tumor microenvironment (TME)." (PMID 36291937, 2022). "In future experiments, we will investigate the specific binding of [11C]PK68 with RIPK1 in PET studies using pathological animal models, such as liver inflammation, peripheral ischemia, and tumor-bearing models." (PMID 35290562, 2022). "The tumor stage can also influence RIPK1 expression levels, for example in HNSCC the metastatic stage shows reduced transcriptional and protein expression levels of RIPK1 compared to primary tumor and this could be associated to epigenetic events such as the methylation status in the RIPK1 promoter." (PMID 33567618, 2021). "In the present study, we made further progress by demonstrating that RIPK1, a cell death regulator, is the key mediator of AQP1-initiated pro-tumor signaling involved in the pathophysiological process of TNBC." (PMID 33980862, 2021). "Although several key necroptosis regulators including receptor interacting protein kinase 1 (RIPK1) have been identified, the regulation of tumor necroptosis during tumor development remains elusive." (PMID 33976222, 2021). "While there is a modest decrease of RIPK1 mRNA level in tumors, the mRNA levels of ZBP1 and RIPK3 are significantly increased in isolated tumor cells." (PMID 33976222, 2021). "Beyond transplantation and tumor immunology, this newly identified function of T cell–derived TNF to enhance T cell cytotoxicity via activation of RIPK1-dependent cell death likely evolved in response to infectious pathogens." (PMID 34752416, 2021). "Necrostatin-1 inhibits receptor-interacting serine/threonine-protein kinase 1 (RIPK1) to initiate necroptosis; it also inhibits indoleamine 2,3-dioxygenase (IDO) to regulate tumor immunity." (PMID 34572979, 2021). "Further screening for proteins related to the tumor chemotherapy sensitivity, inspiringly, gene FADD and its role-related genes RIPK1, found that FADD in the Ca group was highly expressed, and RIPK1 was poorly expressed in the Ca group." (PMID 34262870, 2021). "As a combination of RIPK1 and FADD, the FADDosome has emerged as an important factor in autophagy, tumor growth promotion, and resistance to chemotherapy." (PMID 34262870, 2021). "As both AQP1 accumulation and RIPK1 depletion coexist in TNBC, we first looked for a correlation between the expression profiles of them in the tumor samples detected by Western blotting." (PMID 33980862, 2021). "RIPK1, also known as RIP1, is a main adaptor kinase in several signaling pathways inducing tumor cell apoptosis by activing NF-κB." (PMID 32272907, 2020).